CXCR1 (C-X-C motif chemokine receptor 1)
Diseases named in the same sentence as CXCR1 in open-access papers (continued):
Sharing a sentence is not in itself a finding about the gene and the disease.
metastatic cancer (2 papers, 2021 to 2025). A carcinoma which has spread from the original site of growth to another anatomic site. "Pharmacologic targeting of the IL-8/FOXC1/CXCR1 and FOXC1/NFκB/IL-6 positive feedback loops hold promise for deriving clinical therapeutic benefit in FOXC1+ pro-metastatic cancers." (PMID 34540690, 2021).
metastatic disease (2 papers, 2024 to 2025). "Considering the predominant role of IL‐8–CXCR1/CXCR2 in NETosis, various clinical trials are presently underway intending to determine the efficacy of CXCR1/CXCR2 inhibitors in blocking NETs and controlling metastatic disease treatments." (PMID 39015554, 2024).
mucocutaneous leishmaniasis (2 papers, 2011 to 2024). The most common form of leishmaniasis that is transmitted through the bite of female phlebotomine sand flies or after exposure to leishmania parasites. "Variants at CXCR1 and CXCR2 have been associated with susceptibility to cutaneous and mucocutaneous leishmaniasis in Brazil." (PMID 22171941, 2011).
multiple sclerosis (2 papers, 2017 to 2023). A progressive autoimmune disorder affecting the central nervous system resulting in demyelination. "Here we reported that compared with healthy controls, the level of CXCR1 was aberrantly increased in multiple sclerosis (MS) patients." (PMID 37709757, 2023).
neuropathic pain (2 papers, 2019 to 2020). Chronic pain caused by damage to nerve fibers. "Dual inhibitors of CXCR1/CXCR2 were also tested in the oxaliplatin-induced neuropathic pain model." (PMID 32347537, 2020). "Brandolini and colleagues investigated the effect of reparixin, an inhibitor of CXCR1/CXCR2, in the suppression of the development of paclitaxel-induced neuropathic pain in rats." (PMID 32347537, 2020).
neuropathy (2 papers, 2019 to 2025). A disorder affecting the nervous system that manifests with pain, tingling, numbness, and/or muscle weakness. "We recently reported the efficacy of reparixin, an inhibitor of CXCR1/2, in paclitaxel-induced CIPN in rats, identifying the activation of the IL-8/CXCR1/2 axis as a mechanism strictly implicated in the induction and maintenance of paclitaxel induced-neuropathy." (PMID 31409858, 2019).
Oral Cancer (2 papers, 2021 to 2026). "In a study using the murine oral cancer 2 (MOC2) model, administration of the CXCR1/2 small-molecule inhibitor, SX-682, inhibited MDSC accumulation in the tumor and enhanced the efficacy of NK cell-based adoptive cell transfer therapy." (PMID 34944914, 2021).
ovarian serous cancer (2 papers, 2020 to 2022). "Collectively, this study demonstrated that IL‐8 and IL‐8 receptors CXCR1 and CXCR2 were up‐regulated in advanced ovarian serous cancer tissues." (PMID 31793192, 2020). "In this study, we found that IL‐8 and its receptors CXCR1 and CXCR2 were up‐regulated in advanced ovarian serous cancer tissues." (PMID 31793192, 2020). "Moreover, IL-8 and its receptors (CXCR1 and CXCR2) are upregulated in advanced serous ovarian cancers." (PMID 35867729, 2022). "First, we examined IL‐8, CXCR1 and CXCR2 expression in samples of ovarian serous cancer tissue and found the IL‐8, CXCR1 and CXCR2 were highly expressed in high‐grade ovarian serous cancer tissues than in low‐grade ovarian serous cancer tissues." (PMID 31793192, 2020).
prostate tumor (2 papers, 2020 to 2024). "The baseline and radiation-enhanced secretion of CXCL8 (and its orthologues CXCL1, CXCL2 and CXCL5) from PTEN-deficient prostate tumour epithelial cells exerts both autocrine and paracrine actions within the tumour microenvironment given the expression of CXCR1 and CXCR2 upon multiple cell types." (PMID 32743555, 2020). "Further experiments were conducted to evaluate the impact of CXCR1/2 inhibition upon the response of growing prostate tumours to RT." (PMID 32743555, 2020). "Our in vivo experimentation in three distinct prostate tumour models provides further compelling evidence for the contribution of CXCR1/CXCR2 signalling in adversely affecting RT outcome." (PMID 32743555, 2020). "In this study, we investigated the role of CXCR1 expression in prostate tumor, using the androgen-dependent cell line MDA-PCa-2b to stably express CXCR1 (MDA-PCa-2b-CXCR1) and, for control, cells expressing CXCR2 (MDA-PCa-2b-CXCR2) or vector alone (MDA-PCa-2b-vec)." (PMID 39766038, 2024). "CXCR1 expression, not CXCR2, upregulates the tumor suppressor ITM2A to inhibit prostate tumor growth." (PMID 39766038, 2024).
pulmonary TB (2 papers, 2021 to 2022). "The oxidative burst in neutrophils induced via CXCR1/2 was significantly attenuated in patients with pulmonary TB compared to those with latent TB and healthy individuals." (PMID 35163035, 2022). "Although the frequency of the most abundant subpopulation, CD3− MDMs, decreased, our results are consistent with a previous report indicating the reduced expression of CXCR1 on the granulocytes of patients with pulmonary TB." (PMID 35008755, 2021).
rectal cancer (2 papers, 2011 to 2019). A primary or metastatic malignant neoplasm that affects the rectum. "Another study on interleukin genes and associations with colon and rectal cancer risk and overall survival showed SNPs from genes within the IL-8 pathway (IL8, CXCR1 and CXCR2) to have significant association with both colon and rectal cancer risk." (PMID 31244280, 2019).
renal carcinoma (2 papers, 2019 to 2023). A carcinoma arising from the epithelium of the renal parenchyma or the renal pelvis. "Taken together, our results suggest that the IL‐8/CXCR1 axis is associated with CSC‐like properties in renal cancer with implications for renal cancer treatment." (PMID 30883740, 2019).
renal fibrosis (2 papers, 2021 to 2022). A final common manifestation of a wide variety of chronic kidney diseases characterized by glomerulosclerosis and tubulointerstitial fibrosis. "Studies have proven that blocking CXCR 1/2 can alleviate diabetic mouse kidney inflammation and renal fibrosis." (PMID 34164430, 2021). "Although CXCR1 and CXCR2 are both receptors for IL-8, we assumed that IL-8 could induce renal fibrosis mainly through activating CXCR2." (PMID 35592244, 2022).
small cell lung carcinoma (2 papers, 2013 to 2020). Small cell lung cancer (SCLC) is a highly aggressive malignant neoplasm, accounting for 10-15% of lung cancer cases, characterized byrapid growth, and early metastasis. "Further, CXCL6 acts as an autocrine growth factor in tumor cells itself, i.e., in small cell lung cancer cells expressing its cognate receptors (CXCR1 and CXCR2)." (PMID 31963450, 2020). "Blockade of CXCR1 via neutralizing antibody has been shown to inhibit CXCL8-induced proliferation of small-cell lung cancer (SCLC) cell lines." (PMID 24276377, 2013).
staphylococcus aureus infection (2 papers, 2024 to 2025). An infectious process in which the bacteria Staphylococcus aureus is present. "In the early stages of Staphylococcus aureus infection, the expression levels of several genes encoding pro-inflammatory molecules (IL8, IL1B, OSM, and CXCR1, etc.)show a dramatic increase, with the expression of IL8 increasing up to 8196-fold." (PMID 39065061, 2024). "Specifically, in staphylococcus aureus infections, the LukED toxin enhances neutrophil destruction and NET formation by targeting CXCR1 and CXCR2, thus intensifying the infection’s severity." (PMID 40625358, 2025).
acne inversa (1 paper, 2022). "Several more drugs with new immunological targets such as IL-12/23, IL-17, IL-23, IL-36, C5a, CD-20, CD-40, LTA4, and CXCR1/2 are presently under investigation for the treatment of acne inversa." (PMID 36077114, 2022).
adenomyosis (1 paper, 2024). The growth of endometrial tissue inside the muscular wall of the uterine corpus. "Additionally, the expression of IL-8 receptors, CXCR1 and CXCR2, is increased in adenomyosis lesions, suggesting that IL-8 and its receptors may be involved in the pathogenesis of adenomyosis." (PMID 39595579, 2024).
Allergy (1 paper, 2015). An allergy is an immune response or reaction to substances that are usually not harmful. "Chemokine receptors (CXCR1 and CXCR2) of activated mast cells receive cytokine (CCL5) signals, and stimulated mast cells migrate into the tissue to release histamine, lipid mediators, and other inflammatory cytokines and chemokines to cause serious allergy and inflammation." (PMID 25861366, 2015).
aneurysm (1 paper, 2023). Bulging or ballooning in an area of an artery secondary to arterial wall weakening. "In animal models of AAA, inhibition of CXCR1/2 receptors for IL-8 caused reduced aneurysm growth; therefore, targeting the signaling pathway of this cytokine could be a promising strategy for AAA therapy." (PMID 37569462, 2023).
Anxiety (1 paper, 2019). Intense feelings of nervousness, tension, or panic often arise in response to interpersonal stresses. "To further examine the role of Cxcl1 in anxiety-like behavior, we treated HFD mice with reparixin, which inhibits the Cxcl1 receptors Cxcr1 and Cxcr2." (PMID 30612898, 2019).
bacterial pneumonia (1 paper, 2024). Acute infection of the lung parenchyma caused by bacteria (e.g., Streptococcus pneumoniae, Haemophilus influenzae, Chlamydia pneumoniae, Mycoplasma pneumoniae, and Legionella pneumophila). "C–X–C motif chemokine receptor 1 (CXCR1) is necessary for the activation of inflammatory mediators, CXCR1 antagonism has been proposed as a protective strategy against bacterial pneumonia." (PMID 38601461, 2024).
brain cancer (1 paper, 2025). A primary or metastatic malignant neoplasm affecting the brain. "Taken together, these results suggest that CXCR1 and its ligands GROα and IL-8 were aberrantly expressed in brain cancer cells and that CXCR1 mediated proliferative signaling that was triggered by its ligands via the ERK1/2 pathway." (PMID 40362634, 2025). "Although CXCR2 expression was elevated in all brain cancer cell lines examined, CXCR1 appeared to be more selectively overexpressed in M059J and M059K cell lines up-regulated in GROα and/or IL-8." (PMID 40362634, 2025).
breast fibroadenoma (1 paper, 2017). "Only few cells in normal breast tissues expressed CXCR1 with junior staining, and the percentage of positive cells increased in breast fibroadenoma tissues." (PMID 28454081, 2017).
bronchopneumonia (1 paper, 2020). Acute inflammation of the walls of the terminal bronchioles that spreads into the peribronchial alveoli and alveolar ducts. "Bronchopneumonia and suppurative pneumonia presented higher CXCR1/2 expression than interstitial pneumonia and serous pneumonia." (PMID 31988368, 2020). "Interestingly, the expression of CXCR1/2 in bronchopneumonia and suppurative pneumonia were significantly higher than that in interstitial pneumonia and serous pneumonia." (PMID 31988368, 2020).
Cerebral ischemia (1 paper, 2014). Restriction of arterial blood supply to the brain associated with insufficient oxygenation to support the metabolic requirements of the tissue. "Inhibiting both CXCR1 and CXCR2 decreased polymorphonuclear lymphocyte infiltration and improved neurological function in permanent and transient rat cerebral ischemia." (PMID 24662979, 2014).
chondrosarcoma (1 paper, 2015). A malignant cartilaginous matrix-producing mesenchymal neoplasm arising from the bone and soft tissue. "Specific simultaneous inhibition of CXCR1 and CXCR2 using blocking antibodies in human primary chondrocytes, or by siRNA in the JJ012 human chondrosarcoma cell line, resulted in reduced ECM production in micromass cultures." (PMID 25135253, 2015).
chorioamnionitis (1 paper, 2022). A morphologic finding indicating inflammation of the fetal sac membranes. "We aimed to determine the immunoexpression of CXCR1 in placentas with chorioamnionitis, and its association with adverse perinatal outcomes." (PMID 35453930, 2022). "At present, most studies have focused mainly on IL-8, with limited data on CXCR1 expression in chorioamnionitis." (PMID 35453930, 2022). "The aim of this study was to determine the immunoexpression of CXCR1 in chorioamnionitis." (PMID 35453930, 2022). "Our findings suggest that CXCR1 could be used as a potential biomarker to predict adverse perinatal outcomes in pregnancy with chorioamnionitis." (PMID 35453930, 2022). "CXCR1 was expressed in placentas with and without chorioamnionitis." (PMID 35453930, 2022).
clear cell carcinoma (1 paper, 2020). "We previously verified that CXCR1/2 were expressed in different human OTC lines and showed that epithelial adenocarcinoma cell lines (OVCAR-3, IGROV-1, and SKOV-3 cells) as well as a clear cell carcinoma cell line (JHOC-5) expressed both CXCR1 and CXCR2." (PMID 31504643, 2020).
Cognitive impairment (1 paper, 2017). Abnormal cognition is characterized by deficits in thinking, reasoning, or remembering. "CXCR1 and ERK/p38 MAPK inhibition decreased activation of microglia and blockade of this route also attenuated lesions to the white matter, and the cognitive impairments induced by BCAS." (PMID 28670274, 2017).
cutaneous squamous cell carcinoma (1 paper, 2021). "Keratinocytes can also be stimulated to produce CXCL8, promoting the proliferation and migration of cSCC (cutaneous squamous cell carcinoma) cells, suggesting an important role of the CXCR1/CXCR2 (C-X-C motif chemokine receptor 1/2) axis in UV inflammation and tumorigenesis." (PMID 33513730, 2021).
dengue (1 paper, 2025). "The associations between HERV expression, CXCR1, IL18RAP, and dengue severity represent insights that should be further investigated through functional assays and patient-derived immune cell models." (PMID 40124360, 2025). "Key findings demonstrate the up-regulation of immune-related genes, such as CXCR1 and IL18RAP, along with HERV elements and down-regulated miRNAs in severe dengue patients." (PMID 40124360, 2025). "Even with the challenges of directly interpreting in vitro transcriptomic findings in a physiological context, the concordance of our results with prior in vivo studies strengthens the suggestive potential role of CXCR1 and IL18RAP upregulation in severe dengue." (PMID 40124360, 2025). "Specifically, the upregulation of CXCR1 and IL18RAP genes in patients who progressed to severe dengue correlates with a complex regulatory network involving down-regulated microRNAs (miRNAs) and non-LTR retroviruses, emphasizing their relevance to inflammation and vascular permeability." (PMID 40124360, 2025).
denture stomatitis (1 paper, 2009). Inflammation of the mouth due to denture irritation. "Our results showed a significantly lower expression of CXCR1 and CD62L on neutrophils from patients with Candida-related denture stomatitis than from young controls." (PMID 19327169, 2009). "Blood granulocytes from elderly with or without Candida-related denture stomatitis had a reduced expression of CXCR1, CD62L and CD11b as well as from young patients, which might impair chemotaxis and diapedesis of such cells." (PMID 19327169, 2009).
diffuse astrocytoma (1 paper, 2018). A low-grade (WHO grade II) astrocytic neoplasm. "Further, protein localization study performed on GBM and diffuse astrocytoma FFPE sections using immunohistochemistry established expression of IL-8 in GBM cells and expression of its receptor CXCR1 primarily in tumor-associated vessels and in few cases in tumor cells as well." (PMID 30086759, 2018).
endothelial dysfunction (1 paper, 2017). In vascular diseases, endothelial dysfunction is a systemic pathological state of the endothelium (the inner lining of blood vessels) and can be broadly defined as an imbalance between vasodilating and vasoconstricting substances produced by (or acting on) the endothelium. "Accordingly, future investigations are needed to further elucidate the paracrine role of PGP in other cardiovascular disorders, as well as the relative roles of endothelial CXCR1 and CXCR2 in promoting cytokine-dependent endothelial dysfunction." (PMID 28790330, 2017).
endotoxemia (1 paper, 2016). "Besides, p38 is involved in the down-regulation of neutrophil CXCR1 and CXCR2 during human endotoxemia but the detailed mechanism remains to be discovered." (PMID 27655676, 2016).
epilepsy (1 paper, 2025). A brain disorder characterized by episodes of abnormally increased neuronal discharge resulting in transient episodes of sensory or motor neurological dysfunction, or psychic dysfunction. "The role of CXCL1, a murine ortholog of the human chemokine CXCL8 (IL-8), and its receptors CXCR1 and CXCR2 in epilepsy was discussed in a previous study using a murine model." (PMID 40243443, 2025).
gastritis (1 paper, 2024). Inflammation of the stomach. "Apart from these genes, targets like CCL2, IL6, JAK2, IL2RA and CXCR1 were also of vital importance in the Hot herbs’ targets network, which might infer us that another potential mechanism of Hot herbs against Cold ZEHNG gastritis was to regulate immune responses." (PMID 39367502, 2024).
gastroesophageal reflux disease (1 paper, 2023). A chronic disorder characterized by reflux of the gastric and/or duodenal contents into the distal esophagus. "Study demonstrated that enriched genes including IL1B, CXCR1, FFAR4, VIP (vasoactive intestinal peptide), and GATA3 have been identified as a key candidate genes in patients with gastroesophageal reflux disease." (PMID 38137330, 2023).
heart failure (1 paper, 2014). Inability of the heart to pump blood at an adequate rate to meet tissue metabolic requirements. "In addition, we can also find reports about the increased levels of IL-8, CXCR1 and CXCR2 in CAD patients, which is supposed to be involved in the pathogenic mechanisms in heart failure." (PMID 25514790, 2014).
Hepatic steatosis (1 paper, 2024). Steatosis is a term used to denote lipid accumulation within hepatocytes. "Ibuprofen treatment was also validated to downregulate CXCR1 and CXCR2 in peripheral blood mononuclear cells (PBMCs) and improve glucose tolerance, hypertriglyceridemia, hepatic steatosis, and liver inflammation in lipodystrophy mice." (PMID 38989000, 2024).
Hypertension (1 paper, 2025). The presence of chronic increased pressure in the systemic arterial system. "Like the other receptors already discussed, CXCR1 and CXCR2 play a crucial role in the development of several CVDs, such as atherosclerosis, ischemia, cardiac remodeling, and hypertension." (PMID 40859641, 2025). "The literature mainly highlights the receptors CCR2, CCR5, CXCR1, CXCR2, and CXCR4 as the most relevant for the progression of hypertension." (PMID 40859641, 2025).
idiopathic pulmonary fibrosis (1 paper, 2023). Idiopathic pulmonary fibrosis (IPF) is a nonneoplastic pulmonary disease that is characterized by the formation of scar tissue within the lungs in the absence of any known cause. "Moreover, the demonstration that in interstitial lung disease-idiopathic pulmonary fibrosis (ILD-IPF), IL-8 and its receptor CXCR1 are highly expressed by mesenchymal progenitor cells (MPCs), which are the cellular originators of IPF fibroblasts, is of clinical significance." (PMID 37035302, 2023).
invasive breast carcinoma (1 paper, 2022). A carcinoma that infiltrates the breast parenchyma. "Moreover, a significant upregulation of the CXCR1/2 levels were detected in the invasive breast carcinoma samples in relation to normal breast tissues." (PMID 35954247, 2022).
knee osteoarthritis (1 paper, 2019). "The statistical result of the verification experiment showed that the expression level of ADIPOQ, IL6, and CXCR1 was significantly increased in knee osteoarthritis synovial membranes (p < 0.05)." (PMID 31139654, 2019).
lipodystrophy (1 paper, 2024). A congenital or acquired disorder characterized by abnormal loss or redistribution of the adipose tissue in the body. "For the first time, our research revealed that ibuprofen downregulates CXCR1 and CXCR2 in PBMCs of lipodystrophy, leading to improvements in glucose and lipid metabolism associated with lipodystrophy." (PMID 38989000, 2024).